LAMTOR3 (late endosomal/lysosomal adaptor, MAPK and MTOR activator 3)
Description:
As part of the Ragulator complex it is involved in amino acid sensing and activation of mTORC1, a signaling complex promoting cell growth in response to growth factors, energy levels, and amino acids. Activated by amino acids through a mechanism involving the lysosomal V-ATPase, the Ragulator plays a dual role for the small GTPases Rag (RagA/RRAGA, RagB/RRAGB, RagC/RRAGC and/or RagD/RRAGD): it (1) acts as a guanine nucleotide exchange factor (GEF), activating the small GTPases Rag and (2) mediates recruitment of Rag GTPases to the lysosome membrane. Activated Ragulator and Rag GTPases function as a scaffold recruiting mTORC1 to lysosomes where it is in turn activated. Adapter protein that enhances the efficiency of the MAP kinase cascade facilitating the activation of MAPK2 (By similarity).
Synonyms: Mp1; MAP2K1IP1; MAPKSP1; MAPBP; Ragulator3; PRO0633
Tractability: Small molecule: a structure with a bound ligand is known. Antibody: its Gene Ontology location is reachable by antibodies, with high confidence; UniProt places it where antibodies can reach, with medium confidence. PROTAC: ubiquitination databases record sites on it; its protein half-life has been measured.
Gene: Protein-coding gene on chromosome 4 (99,878,336 to 99,894,428, reverse strand). Ensembl gene ENSG00000109270.
Subcellular location: Late endosome membrane
Pathways (Reactome):
Signal Transduction: Energy dependent regulation of mTOR by LKB1-AMPK; MAP2K and MAPK activation; MTOR signalling; Regulation of PTEN gene transcription; mTORC1-mediated signalling
Autophagy: Macroautophagy
Cellular responses to stimuli: Amino acids regulate mTORC1
Immune System: Neutrophil degranulation
Gene Ontology:
Molecular function: guanyl-nucleotide exchange factor activity; molecular adaptor activity; protein binding; kinase activator activity
Biological process: cellular response to amino acid stimulus; cellular response to nutrient levels; intracellular protein localization; positive regulation of TOR signaling; positive regulation of TORC1 signaling; TORC1 signaling; positive regulation of intracellular signal transduction; regulation of TOR signaling
Cellular component: extracellular exosome; FNIP-folliculin RagC/D GAP; focal adhesion; lysosomal membrane; Ragulator complex; endosome membrane; late endosome membrane; plasma membrane; specific granule membrane; tertiary granule membrane; cytoplasm; late endosome
Genetic constraint (gnomAD): Loss-of-function variants: 7 observed, 7.75 expected, observed/expected ratio (o/e) 0.9, 90% interval 0.51 to 1.64. That is too few expected variants to judge how well the gene tolerates losing a copy. Missense variants: 58 observed, 62.9 expected, observed/expected ratio (o/e) 0.92, 90% interval 0.75 to 1.15. Synonymous variants: 12 observed, 21.06 expected, observed/expected ratio (o/e) 0.57, 90% interval 0.36 to 0.92.
Homologues: Orthologues: chimpanzee LAMTOR3 (100% identical), macaque LAMTOR3 (100% identical), mouse Lamtor3 (98% identical), rabbit LAMTOR3 (98% identical), rat Lamtor3 (97% identical), guinea pig LAMTOR3 (95% identical), zebrafish lamtor3 (88% identical), tropical clawed frog lamtor3l (86% identical), pig LAMTOR3 (78% identical), Drosophila melanogaster Lamtor3 (44% identical), Caenorhabditis elegans lmtr-3 (18% identical).
Diseases named in the same sentence as LAMTOR3 in open-access papers:
LAMTOR3 is named in the same sentence as 25 diseases in open-access papers, as found by Europe PMC text mining. Sharing a sentence is not in itself a finding about the gene and the disease. The quoted sentences say what the papers report.
breast carcinoma (2 papers, 2013 to 2020). "Our aim was to address the possible role of genetic polymorphisms in LAMTOR2 and LAMTOR3 as genetic risk factors for breast cancer." (PMID 23341997, 2013). "We initially hypothesized that somatic, cancer-tissue-specific mutations in LAMTOR2 and LAMTOR3 could be associated with breast cancer progression and metastasis." (PMID 23341997, 2013). "Therefore, future studies including a dense map of SNPs from the LAMTOR complex including the regulatory regions might reveal implications of genetic associations of LAMTOR2 and LAMTOR3 with breast cancer." (PMID 23341997, 2013). "Due to the well established role of both signalling cascades in breast cancer progression, and the recent implication of LAMTOR3 in oestrogen receptor positive breast cancer, we leave open the possibility of therapeutically targeting the complex as previously proposed by others." (PMID 23341997, 2013). "In addition, a recent publication reported that LAMTOR3 (Mp1) was required for the survival of oestrogen receptor positive breast cancer cell lines." (PMID 23341997, 2013). "Sequencing of the exons and exon-intron boundaries of both LAMTOR2 and LAMTOR3 revealed three SNPs to occur in a sequencing sample of 50 breast cancer patients, but no novel mutations." (PMID 23341997, 2013). "The identified polymorphisms in LAMTOR2 and LAMTOR3 do not seem to play a relevant role in breast cancer." (PMID 23341997, 2013). "The present work does not exclude that the observed polymorphisms may play a role in other disease contexts or that other not yet identified polymorphisms in LAMTOR2 and LAMTOR3 may in fact contribute to breast cancer aetiology." (PMID 23341997, 2013). "We sequenced the exons and exon–intron boundaries of LAMTOR2 (p14) and LAMTOR3 (MP1) in 50 prospectively collected pairs of cancerous tissue and blood samples from breast cancer patients and compared their genetic variability." (PMID 23341997, 2013). "As our sequencing sample was relatively small (n = 50), and as the SNP rs148972953 in LAMTOR3 had a minor allele frequency (MAF) of 4%, we investigated whether a healthy working population sample would show different genotype distributions than the breast cancer sample." (PMID 23341997, 2013). "Although the LAMTOR complex was independently demonstrated to be involved in breast cancer, neither LAMTOR2 nor LAMTOR3 came up as hits in genome-wide association studies (GWAS) with any kind of disease or trait as indexed by the catalogue of published GWAS." (PMID 23341997, 2013).
Alzheimer disease (1 paper, 2023). A progressive, neurodegenerative disease characterized by loss of function and death of nerve cells in several areas of the brain leading to loss of cognitive function such as memory and language. "Recent transcriptional profiling of the olfactory pathway of female African green monkeys, a well-described model of early Alzheimer’s disease-like neuropathology, has suggested that LAMTOR3 is involved in Alzheimer’s disease phenotypes." (PMID 37173755, 2023).
aneurysm (1 paper, 2022). Bulging or ballooning in an area of an artery secondary to arterial wall weakening. "This MAPK node connected to LAMTOR3 and WASF2, two proteins identified in all three aneurysm groups." (PMID 35990960, 2022).
Batten disease (1 paper, 2025). "A recent paper exploring the proteomic changes in microglia with another LSD, Batten disease caused by loss of CLN3, identify similar changes to those seen here, including increased TTYH3, PTTG1IP, LAMTOR3, PSAP, STARD3NL, TSPAN7, TMEM192 and NPC1." (PMID 40608809, 2025).
glioblastoma (1 paper, 2023). The most malignant astrocytic tumor (WHO grade IV). "The requirement for LAMTOR3 in EV71 replication was further confirmed in human rhabdomyosarcoma RD cells, human neuroblastoma SK-N-SH cells, and human glioblastoma U251 cells, in which we observed significantly reduced viral RNA replication after LAMTOR3 KO or knockdown." (PMID 37906052, 2023).
invasive ductal breast carcinoma (1 paper, 2013). The most common type of invasive breast carcinoma, accounting for approximately 70% of breast carcinomas. "In addition, LAMTOR3 (Mp1) was also found to be up-regulated in invasive ductal breast carcinomas." (PMID 23341997, 2013).
kidney cancer (1 paper, 2025). Primary or metastatic malignant neoplasm involving the kidney. "After 72 h of shikonin treatment, the expression of genes JNK1 and LAMTOR3 evidently increased in both cell lines of the studied human kidney cancer." (PMID 41462911, 2025). "In the A-498 kidney cancer cell, a positive correlation (p < 0.05) was observed between miR-181a expression and the mRNA expression of FOXO1, FOXO3, PDCD4, AKT3, JNK1 and LAMTOR3." (PMID 41462911, 2025).
oesophageal cancer (1 paper, 2013). "However, the region 4q23, in which LAMTOR3 is located, showed signals of associations with upper aerodigestive tract cancers and oesophageal cancer indicating that the region per se is interesting for cancer." (PMID 23341997, 2013).
ovarian carcinoma (1 paper, 2022). A malignant neoplasm originating from the surface ovarian epithelium. "Conclusion: 1) MiR-8485 may be the key factor of BJOE in promoting autophagy and apoptosis and inhibiting cell proliferation of ovarian cancer cells; 2) BJOE may play an antitumor role by regulating LAMTOR3/mTOR/ATG13 signaling axis through miR-8485 to promote autophagy in ovarian cancer cells." (PMID 35959437, 2022).
pancreatic neoplasm (1 paper, 2020). A benign or malignant neoplasm involving the pancreas. "As LAMTOR3‐guided ERK and AKT are both important downstream signal pathways of K‐Ras, the oncogenic mutation is present in 90% of pancreatic neoplasms, as well as a research hot spot of drug therapeutic target." (PMID 33184989, 2020).
renal clear cell carcinoma (1 paper, 2024). "In addition, LAMTOR3 expression was significantly decreased in renal clear cell carcinoma compared with normal renal tissue." (PMID 38246894, 2024). "LAMTOR3 may be a potential marker for the diagnosis and treatment of renal clear cell carcinoma." (PMID 38246894, 2024).
rhabdomyosarcoma (1 paper, 2023). A rare aggressive malignant mesenchymal neoplasm arising from skeletal muscle. "The requirement for LAMTOR3 in EV71-induced cell death was further confirmed in human rhabdomyosarcoma RD cells, where deletion of LAMTOR3 also efficiently reduced the percentage of PI-positive cells after EV71 infection." (PMID 37906052, 2023).
cancer (5 papers, 2013 to 2024). A tumor composed of atypical neoplastic, often pleomorphic cells that invade other tissues. "Through meta-analysis, PCR super-array, and subsequent biochemical assays, the induction of MEK partner-1 (MP1, encoded by the LAMTOR3 gene) was shown to play an important role in maintaining ERK1/2 activity during the acquisition of cancer stemness under spheroid culture conditions." (PMID 28830458, 2017). "In recent years, LAMTOR3 and CD59 have been extensively used to inhibit the development of a variety of cancers." (PMID 34803519, 2021). "Using F3.EGFRviii CNSCs model, we demonstrated LAMTOR3 in GBM served as an important signaling mediator to control MEK1/ERK1/2 pathway, of which activation contributed to maintaining ‘neural cancer stemness’." (PMID 28830458, 2017).
tumour (1 paper, 2013). "We found one single nucleotide polymorphism (SNP) in LAMTOR2 (rs7541) and two SNPs in LAMTOR3 (rs2298735 and rs148972953) in both tumour and blood samples, but no somatic mutations in cancerous tissues." (PMID 23341997, 2013). "Our hypothesis that LAMTOR2 and LAMTOR3 gene regions would harbour somatic mutations in tumour tissue was not confirmed; all SNPs that were found were present in both benign (DNA derived from whole blood) and cancerous tissue." (PMID 23341997, 2013).
LAMTOR3 also shares sentences with these, for which no sentence is quoted: gastric cancer (2 papers); glioma (2); arteritis (1); brain tumors (1); colorectal cancer (1); infection (1); ischemia (1); myocardial infarction (1); neuroblastoma (1); pancreatic carcinoma (1); prostate carcinoma (1).